CCR1 (C-C motif chemokine receptor 1)
Diseases named in the same sentence as CCR1 in open-access papers (continued):
Sharing a sentence is not in itself a finding about the gene and the disease.
autoimmune disease (10 papers, 2014 to 2025). A disorder resulting from loss of function or tissue destruction of an organ or multiple organs, arising from humoral or cellular immune responses of the individual to their own tissue constituents. "CCR1 mediates inflammatory responses and plays an essential role in the development of autoimmune diseases." (PMID 41542175, 2025). "Those compounds were colistimethate sodium, a broad-spectrum antibiotic; flubendazole, which has been repurposed to inhibit cancer cell growth; and BX471, a CCR1 antagonist, which has shown promise in modulating proinflammatory and autoimmune diseases." (PMID 39329775, 2024). "CCR1 has affinity for multiple chemokines, and CCR1 antagonists have been tested against autoimmune diseases in clinical trials." (PMID 33525500, 2021). "CCR1 has been considered a drug target for treating allergic and autoimmune diseases." (PMID 41542175, 2025). "CCR1 has been considered an attractive drug target for treating autoimmune diseases and tumors." (PMID 41542175, 2025). "CCR1 is an inflammatory chemokine receptor that is expressed by immune cells, and has been shown to be important in a number of pathologies, including sepsis, viral infections, cancer and autoimmune disease." (PMID 32467242, 2020). "CCR1 and CCR5 regulate the progression of these diseases differently, and thus the elucidation of the roles of CCR1 and CCR5 would provide clues for understanding the mechanisms underlying the progression of these autoimmune diseases." (PMID 26472202, 2015). "Since CCR1 blockade is known to inhibit recruitment of not only macrophages but also CD4+ T-cells to nephritic kidneys in an autoimmune disease mouse model, we were concerned that the phenotype observed in our experiments could be attributed to affects on the T-cell populations rather than IMCs." (PMID 26183450, 2015). "RANTES, an inflammatory chemokine that has receptors, including CCR1, CCR3, and CCR5, can recruit immune cells to inflammatory sites and is involved in autoimmune diseases." (PMID 36173680, 2022). "C–C chemokine receptor 1 (CCR1) and CCR5 are involved in various inflammation and immune responses, and regulate the progression of the autoimmune diseases differently." (PMID 26472202, 2015). "CCR1 and CCR5 are therapeutic targets for autoimmune diseases, multiple sclerosis (MS) and rheumatoid arthritis." (PMID 26472202, 2015). "Therefore, genetic analyses of CCR1 and CCR5 would provide clues toward elucidating how CCR1 and CCR5 affect the progress of MS and other autoimmune diseases." (PMID 26472202, 2015). "Met-CCL5 antagonizes CCR1 and CCR5 activation and function in response to their natural ligands CCL3-5, and this blockade is able to reduce inflammation in models of induced inflammatory and autoimmune diseases, but also after MI." (PMID 24512349, 2014).
prostate carcinoma (10 papers, 2014 to 2025). A carcinoma that arises from epithelial cells of the prostate gland. "In a cell culture setup, the CCR1/CCL5 interaction supports the invasion of taxane-resistant prostate cancer cells through the activation of ERK and Rac signaling pathways." (PMID 40076892, 2025). "The study emphasizes the importance of CCR1 in the development of taxane-resistant prostate cancer." (PMID 40076892, 2025). "Additionally, elevated CCL16 (ligand of CCR1) expression exerted anticancer effects in mice with breast, colon, and prostate cancers." (PMID 38552222, 2024). "RANTES (CCL5) is an important member of the CC subfamily of chemokines, which has an important role in promoting proliferation, angiogenesis, metastasis and drug resistance of prostate cancer cells via its crosslinking with chemokine (C-C motif) receptor 5 (CCR5) or CCR1." (PMID 35804830, 2022). "A CCR3 neutralizing monoclonal antibody (mAb) gave similar results (50% inhibition compared with control) and migration was unaffected by a mAb against CCR1, which is not expressed by prostate cancer cells." (PMID 26756352, 2016). "Interaction between CCR1 and CCL5 promotes the invasion of taxane-resistant PC3 prostate cancer cells by increasing the secretion of MMP-2 and -9 via ERK and Rac activation suggesting that CCR1 could be a novel therapeutic target for taxane-resistant prostate cancer." (PMID 24523569, 2014). "Like all prostate cancer cells studied so far, TRAMP-C1P3 expressed the CCR3 receptor but not CCR1." (PMID 26756352, 2016).
viral infection (10 papers, 2013 to 2025). "The minor allele is associated with increased CCR1 gene expression in cultured fibroblasts (GTEx V8), suggesting that it might function through expression regulation of CCR1, receptor for a C-C type chemokine which play an important role in immune system against viral infection." (PMID 36531218, 2022). "A greater number of genes are upregulated in DCs after MRV infection, many of which are involved in the innate immune response (i.e. Ifit1, Ifit3, Mx1, Gbp2, Oasl1, Isg15, Ccr1, Ifitm2, Oaxl2, Casp1, Casp4) that would be predicted in response to a viral infection." (PMID 38895117, 2024). "Nonetheless, the simultaneous increase in NK- and T-cells, up regulation of CCL5 by NK cells and increased expression of CCR1 and CCR5 receptors by microglia indicate a coordinated response across the innate and adaptive immune systems in response to peripheral viral infection." (PMID 39175524, 2024). "CCR1, CCR2, and CCR5 upregulations could enhance lung infiltration by monocytes and macrophages upon viral infection and mediate hyperinflammation and organ damage in the aftermath." (PMID 36232655, 2022). "In the case of human metapneumovirus (HMPV) and human respiratory syncytial virus (HRSV), viral infection of monocyte-derived DCs did not efficiently decrease CCR1, 2, and 5 expression, and did not efficiently increase CCR7 expression." (PMID 23301113, 2013). "It is also remarkable that the viral infection activated expression of two molecules that are typically expressed by T cells, although CCR1 has been detected in a subpopulation of non-germinal center B cells and CCL4 is released after B cell receptor stimulation." (PMID 40389409, 2025).
glioma (9 papers, 2017 to 2025). A benign or malignant brain and spinal cord tumor that arises from glial cells (astrocytes, oligodendrocytes, ependymal cells). "The precise mechanism of CCR1 signaling in tumor associated macrophages in stimulating glioma cell invasion remains to be determined and will be the subject of future studies." (PMID 36982211, 2023). "Here we show that CCR1 is upregulated in glioma associated macrophages and therefore CCR1 antagonists might preferentially interfere with tumor associated macrophages over normal tissue macrophages." (PMID 36982211, 2023). "Whereas certain other reports showed that higher CCR1 expression was accompanied by a worse outcome of glioma, lung cancer, renal cancer, and testicular cancer." (PMID 38552222, 2024). "In this study, we demonstrate an important role for the chemokine receptor CCR1 in mediating microglia/TAM stimulated glioma invasion." (PMID 36982211, 2023). "Using two structurally unrelated CCR1-specific antagonists we show that CCR1 is necessary for TAM activation of glioma invasion in-vitro." (PMID 36982211, 2023). "There are two reports we are aware of that directly attempt to address the role of CCR1 in glioma pathogenesis." (PMID 36982211, 2023). "The importance of CCR1 in mediating glioma invasion was further underscored by the fact that GL261 conditioned media strongly upregulates CCR1 levels and several CCR1-specific ligands (most prominently CCL3) in MG cells." (PMID 36982211, 2023). "There was a clear dose dependent effect of CCR1 inhibition with 1 uM of MG-1-5 enough to completely inhibit MG-stimulated glioma invasion." (PMID 36982211, 2023). "To examine the effect of CCR1 inhibition on TAM stimulation of glioma invasion, we employed the murine glioma (GL261) and microglia in-vitro coculture model which we previously developed." (PMID 36982211, 2023). "It remains entirely possible that CCR1 signaling on both TAMs and glioma cells play a role in invasion." (PMID 36982211, 2023). "We wanted to assess if there is any crosstalk between the CSF-1R and CCR1 pathways in glioma-stimulated microglia." (PMID 36982211, 2023). "Discovery of high CCR1 levels on tumor stimulated microglia is suggestive this pathway is involved in a paracrine interaction between glioma cells and macrophages." (PMID 36982211, 2023). "The CSF-1R specific antagonist “JnJ”, is able to partially inhibit the induction of CCR1 mRNA by GL261 glioma conditioned media." (PMID 36982211, 2023). "Other chemokine:chemokine receptor systems appear to have redundant roles, determined from studies in murine glioma models, including CCR1 and CCR5 and their shared ligands." (PMID 36685592, 2022). "Although this has not been exhaustively documented in patient tissue thus far, insights in CCR1 activity in glioma are currently emerging (see Section 4)." (PMID 35008294, 2021). "To test the effects of IGF-1 on endogenous levels of IL-1b and CCR1 in glioma cells, we measured mRNA and protein levels of IL-1b and CCR1 in IGF-1-stimulated glioma cells by real-time qPCR assays and immunoblotting analyses." (PMID 28389653, 2017). "Since previous results showed that higher IL-1b and CCR1 levels were found in GBM array data of TCGA, we also measured endogenous protein levels of IL-1b and CCR1 in astrocyte and glioma cell lines." (PMID 28389653, 2017). "Here we have investigated the role of CCR1 in TAM-stimulated glioma invasion." (PMID 36982211, 2023). "Here we extend the findings that CCR1 is involved in cancer invasion and metastasis to glioma, and propose that novel CCR1 antagonists could be very useful for anti-metastatic therapy." (PMID 36982211, 2023). "Interestingly, treatment of a murine microglia cell line with glioma conditioned media resulted in a strong induction of CCR1 gene and protein expression." (PMID 36982211, 2023).
glioma (continued). "To investigate the potential role of CCR1 in TAM stimulation of glioma invasion, we utilized a modified version of a Matrigel-coated transwell assay in which fluorescently labelled glioma cells are cocultured with a spontaneously immortalized murine microglial cell line (MG)." (PMID 36982211, 2023). "Finally, reduced endogenous miR-181d and increased IL-1b/CCR1 levels were identified in IGF-1-stimulated glioma cells." (PMID 28389653, 2017). "IL-1b and CCR1 protein levels were higher in glioma cells than that in astrocyte cells." (PMID 28389653, 2017). "Consequently, IGF-1-enhanced cytokine IL-1b and CCR1 signaling via inhibiting miR-181d is involved in glioma progression." (PMID 28389653, 2017). "We next explored if glioma tumor cells could influence expression of CCR1 in microglia." (PMID 36982211, 2023). "However, in order to formally rule out involvement of glioma-expressed CCR1 in microglia stimulated invasion, cell-specific knockout approaches (i.e., RNA interference and CRISPR/CAS9) will be employed to deplete CCR1 from either the glioma cells or MG microglia." (PMID 36982211, 2023). "Furthermore, by treating with IL1b recombinant proteins, or respectively transfecting with CCR1 and miR-181d genes, we found that both IL-1b and CCR1 could obviously induce glioma cell invasion." (PMID 28389653, 2017). "However, little is known about the roles of CCR1 in glioma progression." (PMID 28389653, 2017). "Two hundred and seventy-nine glioma patients were recruited and grouped according to their genotypes of rs7853346 in PTENP1 and rs1799864 in CCR1." (PMID 37047356, 2023). "Using two structurally distinct CCR1 antagonists, including a novel inhibitor “MG-1-5”, we were able to block microglial activated GL261 glioma cell invasion in a dose dependent manner." (PMID 36982211, 2023). "The observation that CCR1 knockout does not result in glioma tumor growth is not surprising however given that we have never observed any effect of microglia on the proliferation rate of glioma cells in vitro or in-vivo." (PMID 36982211, 2023). "Furthermore, we show that mRNA for CCR1 and CCR1 ligands, including CCL3, are strongly upregulated in a microglial cell line treated with glioma conditioned media." (PMID 36982211, 2023). "In both datasets, CCR1 and CX3CR1 expression strongly correlated with the “macrophage” and “myeloid cell” signatures, while the two receptors were virtually absent from other cell types, unsurprisingly pointing to their key role in immune cell recruitment and function in gliomas." (PMID 35008294, 2021). "One of the limitations of the present study is that we cannot definitively claim it is CCR1 on TAMs, as opposed to the GL261 glioma cells which is mediating invasion, since we are using pharmacological inhibition to globally inhibit CCR1 activity." (PMID 36982211, 2023).
influenza (9 papers, 2009 to 2023). An acute viral infection of the respiratory tract, occurring in isolated cases, in epidemics, or in pandemics; it is caused by serologically different strains of viruses (influenzaviruses) designated A, B, and C, has a 3-day incubation period, and usually lasts for 3 to 10 days. "There is limited evidence showing that both cigarette smoke and influenza infection can upregulate CCR1 expression." (PMID 34203121, 2021). "Neutrophils isolated from influenza-infected mouse lungs were stimulated with CCR1, CCR5, CXCR2, and CXCR3 specific ligands CCL3, CCL4, IL-8, and CXCL11 (100 ng/mL), respectively, and incubated for 4 h." (PMID 31041196, 2019). "Influenza infection also modulates expression and chemotactic responsiveness of CCR1 and CCR2 in monocytes." (PMID 31041196, 2019). "To test if targeting of the stem domain to CCR1/3/5 could lead to more efficient protection against influenza, we constructed a vaccine where the MHCII-specific targeting unit was replaced with MIP1α (MIP1α-H1stem)." (PMID 32269566, 2020). "Bone marrow cells from naïve mice and lung cells from influenza-infected mice were analyzed by flow cytometry to test whether CCR1 and CX3CR1 could be detected at the protein level." (PMID 32174921, 2020). "However, stimulation of CCR1 enhanced NETosis and chemotaxis, thus indicating that induced CRs exhibit differential functional responsiveness during influenza." (PMID 31041196, 2019). "Neutrophils isolated from influenza-infected mouse lungs were stimulated with CCR1, CCR5, CXCR2, and CXCR3 specific ligands including CCL3, CCL4, IL-8, and CXCL11 (100 ng/mL) for 20 min, followed by incubation with a 1:10 ratio of Streptococcus pneumoniae (serotype 3) for 90 min." (PMID 31041196, 2019). "The findings demonstrated that the mRNA levels of CCR5, CCR2, CCR1 and CXCR2 genes were increased after influenza infection." (PMID 37957672, 2023). "While conferring protection against influenza, targeted delivery of HA to MHC-II molecules, CCR1/3/5, or Xcr1 revealed qualitative differences in induced immune responses." (PMID 26257735, 2015). "On the contrary, naïve bone marrow MCp, but not lung MCp from influenza-infected mice, demonstrated a consistent cell surface expression of CCR1." (PMID 32174921, 2020). "Nevertheless, surface expression of CCR1 or CX3CR1 could not be detected on the MCp from influenza-infected lungs." (PMID 32174921, 2020). "In previous work, we demonstrated that the actions of the chemokine, CCL3, signaling via its receptor CCR1, were crucial for granulocyte recruitment to the lungs in response to PVM infection; CCL3 has also been shown to be a crucial mediator of granulocyte recruitment in mouse models of influenza." (PMID 19298652, 2009). "Lung-recruited neutrophils induced CCR1, CCR2, CCR3, CCR5, CXCR1, CXCR3, CXCR4, which were absent or marginally induced in peripheral blood neutrophils from influenza-infected mice." (PMID 31041196, 2019).
liver fibrosis (9 papers, 2010 to 2022). "In experimental murine models, the chemokine receptors CCR2, CCR1 or CCR5 that are differentially expressed on monocyte subsets have been implicated in hepatic fibrosis progression." (PMID 20548789, 2010). "By using different mouse models for liver fibrosis such as bile duct ligation or treatment with carbon tetrachloride, it was shown that both CCR1 and CCR5 promote hepatic fibrosis." (PMID 24646914, 2014). "The effects of CCL3 make this CCR1/CCR5 ligand attractive for further evaluation in experimental liver fibrosis." (PMID 23799074, 2013). "Additionally, use of CCR1-, CCR2-, CCR5-, and CCR8-deficient mice or pharmacological inhibition of these axes reduced hepatic macrophage infiltration, hepatic fibrosis, and hepatocellular damage in experimental models of chronic liver injury." (PMID 31921154, 2019). "Moreover, CCR1 and CCR5 deficient mice showed a lower degree of liver fibrosis after chronic carbon tetrachloride (CCl4) treatment or bile duct ligation (BDL)." (PMID 23799074, 2013). "For instance, the overexpression of CCR1, CCR5, and CXCL4 can contribute to progression of liver fibrosis, whereas the stimulation of CXCR3 and CXCL9 exert the protective function of liver fibrosis." (PMID 35656309, 2022). "In experimental models of liver fibrosis (CCl4 and bile duct ligation), CCR1- and CCR5-knockout mice showed decreased hepatic fibrosis and macrophage infiltration." (PMID 34685739, 2021). "CCR1 mediates its pro-fibrotic effects predominantly through hematopoietic cells, whereas CCR5 mediates liver fibrosis mainly through resident liver cells." (PMID 23799074, 2013). "Also, some previous studies indicated that, while inhibition of CCR1 and CCR5 inhibited the progression of liver fibrosis in mice, concentrations of CCl4 and CCl3 increased in mouse liver fibrogenesis models and cirrhotic patients." (PMID 33042108, 2020). "In addition, neutralization studies identified important roles for both CCR1- and CCR5-expressing macrophages in the development of liver fibrosis." (PMID 24646914, 2014). "By contrast, liver fibrosis development in MDR2 deficient mice is only dependent on CCR5 but not on CCR1, thus confirming the role of CCR5 as promotor of liver fibrosis." (PMID 24646914, 2014). "Interestingly, CCR1 mediates its pro-fibrogenic effects predominantly through hematopoietic cells, whereas CCR5 mediates liver fibrosis mainly through resident liver cells, especially through hepatic stellate cells." (PMID 23799074, 2013). "Importantly, administration of mice with Met-CCL5, a CCR1/CCR5 antagonist, attenuated liver fibrosis and accelerated the regression of fibrosis during follow-up." (PMID 23799074, 2013). "Moreover, CCR1 and CCR5, receptors for the chemokines CCL3/MIP1α, CCL4/MIP1β and CCL5/RANTES, promote liver fibrosis in mice." (PMID 20548789, 2010). "Mechanistically, the murine models lacking CCR1 and CCR5 show a reduced degree of liver fibrosis." (PMID 33042108, 2020).